YTHDF1 (YTH N6-methyladenosine RNA binding protein F1)
Diseases named in the same sentence as YTHDF1 in open-access papers (continued):
Sharing a sentence is not in itself a finding about the gene and the disease.
cervical carcinoma (37 papers, 2020 to 2025). A carcinoma arising from either the exocervical squamous epithelium or the endocervical glandular epithelium. "YTHDF1 was overexpressed in cervical cancer, and significantly associated with the bad prognosis of the patients." (PMID 36707507, 2023). "Among these risk factors, elevated YTHDF1 expression was linked to a poor prognosis in cervical cancer patients, and it was thought to be an oncogene in the disease." (PMID 36091006, 2022). "In this study, we show that YTHDF1 is highly expressed in cervical cancer, and is closely associated with the poor prognosis of cervical cancer patients." (PMID 33816306, 2021). "In this study, we showed that YTHDF1 was highly expressed in cervical cancer, and was closely associated with the poor prognosis of cervical cancer patients." (PMID 33816306, 2021). "To explore the underlying mechanisms of YTHDF1 in cervical cancer, we analyzed online meRIP-seq data (GSE46705), PAR-CLIP and RIP-seq data (GSE63591) to identify the targets of YTHDF1 in cervical cancer cells." (PMID 33816306, 2021). "Furthermore, high levels of METTL3 and YTHDF1 expression in cervical cancer patients were linked to a poor prognosis." (PMID 36091006, 2022). "Significantly, METTL3 also enhances the stability of HK2 mRNA through YTHDF1 mediated m6A modification, thereby promoting aerobic glycolysis in cervical cancer." (PMID 40097750, 2025). "In the volume calculation, the YTHDF1 silencing repressed the tumor volume of cervical cancer cells, as well as the tumor weight." (PMID 39557826, 2024). "Data also showed that upregulated YTHDF1 mRNA in cervical cancer patients was strikingly negatively correlated to the levels of CD8+ T cells." (PMID 39557826, 2024). "In cervical cancer cells, YTHDF1 modulation of RANBP2 translation in an m6A‐dependent manner enhances cell growth, migration and invasion, making it a critical target for cervical cancer therapy." (PMID 39135292, 2024). "Additional studies have analyzed RIP-seq, meRIP-seq, and ribosome profiling sequencing (Ribo-seq) data after YTHDF1 knock-down and found that RAN Binding Protein 2 (RANBP2) is a key target of YTHDF1 in cervical cancer cells." (PMID 39342406, 2024). "In the co-culture of tumor cells with CD8+ T cells, YTHDF1 overexpression promoted the survival rate of cervical cancer cells and reduced the apoptosis of cervical cancer cells." (PMID 39557826, 2024). "The extracellular acidification rate showed that YTHDF1 overexpression promoted the glycolysis of cervical cancer cells, and YTHDF1 silencing inhibited the glycolysis." (PMID 39557826, 2024). "In contrast, METTL3 boosts cervical cancer cell proliferation by enhancing HK2 stability via YTHDF1 recruitment." (PMID 39219199, 2024). "In the cervical cancer samples, the level of YTHDF1 significantly elevated as comparing to the normal controls." (PMID 39557826, 2024). "Taken together, the data illustrated that MCT1 was targeted by YTHDF1 in cervical cancer immune microenvironment." (PMID 39557826, 2024). "Clinically, high expression of YTHDF1 predicted unfavorable clinical outcomes of cervical cancer, which was negatively correlated with CD8+ T cell infiltration." (PMID 39557826, 2024). "Taken together, YTHDF1 hampered the cytotoxic CD8+ T cell’s killing effect to cervical cancer cells." (PMID 39557826, 2024). "YTHDF1 occupies a crucial role in modulating cancer metabolism and promoting tumorigenesis in cervical cancer cells." (PMID 39342406, 2024). "The T cells’ cytotoxicity assay based on LDH release indicated that the cytotoxic activity of CD8+ T cells against YTHDF1 high-expression transfected cervical cancer cells was markedly lower than that of cells transfected with controls." (PMID 39557826, 2024). "CD8+ T cells’ cytotoxicity analysis revealed that YTHDF1 overexpression repressed the survival rate of cervical cancer cells, and reduced the CD8+ T cells’ cytotoxicity." (PMID 39557826, 2024).
cervical carcinoma (continued). "Collectively, our results revealed an oncogenic role played by YTHDF1 in cervical cancer through m6A/MCT1-dependent manner." (PMID 39557826, 2024). "YTHDF1 upregulated in the cervical cancer tissue and cells and correlated to the poor prognosis and CD8+ T infiltration." (PMID 39557826, 2024). "In this study, our findings demonstrated the significant function of YTHDF1 in promoting cervical cancer cells’ immune escape." (PMID 39557826, 2024). "Results illustrated that YTHDF1 predicted unfavorable clinical outcomes of cervical cancer, which was negatively correlated with CD8+ T cell infiltration." (PMID 39557826, 2024). "Survival analysis illustrated that YTHDF1 overexpression promoted the survival rate of cervical cancer cells in the coculture system in different E:T ratio (effector:target ratio)." (PMID 39557826, 2024). "In the present research, the findings revealed that YTHDF1 was remarkably upregulated in the cervical cancer tissue sample and cells." (PMID 39557826, 2024). "PD-L1 expression increased dramatically in cervical cancer tissues and was significantly linked to ALKBH5, FTO, METTL3, RBM15B, YTHDF1, YTHDF3, and ZC3H13 expression levels." (PMID 36091006, 2022). "The knockdown of YTHDF1 will inhibit the proliferation, invasion and metastasis of cervical cancer cells." (PMID 35676619, 2022). "For instance, patients with greater levels of YTHDF1 in cervical cancer had a poor prognosis, and YTHDF1 knockdown reduced the carcinogenesis of cervical cancer cells." (PMID 36091006, 2022). "At the same time, knockdown of RANBP2 reversed the effect of overexpression of YTHDF1 on cervical cancer progression, indicating that YTHDF1 promotes cervical cancer progression by regulating RANBP2 expression in an m6A-dependent manner." (PMID 35707365, 2022). "METTL3 enhanced the HK2 stability through YTHDF1-mediated m6A modification, thereby promoting the Warburg effect in cervical cancer." (PMID 36058934, 2022). "We revealed higher levels of ZC3H13, WTAP, HNRNPC, YTHDF3, and VIRMA were significantly associated with worse outcomes in CESC (HR > 1, blue background), while YTHDC1, YTHDF1 were protective factors of cervical cancer (HR < 1, orange background)." (PMID 35581263, 2022). "Together, our study demonstrates the oncogenic role of YTHDF1 in cervical cancer by regulating the expression of RANBP2." (PMID 33816306, 2021). "Through in vitro experiments we found that YTHDF1 depletion substantially inhibited the proliferation, migration and invasion of cervical cancer cells and promoted apoptosis." (PMID 33816306, 2021). "Results showed that the expression level of YTHDF1 in cervical cancer was higher than that in normal cervical epithelium." (PMID 33816306, 2021). "Here, we found that YTHDF1 is up-regulated in cervical cancer tissues and predicts the poor clinical outcomes." (PMID 33816306, 2021). "CCK-8 assays demonstrated that knocking down YTHDF1 substantially inhibited the proliferation of cervical cancer cells." (PMID 33816306, 2021). "In order to further confirm the expression of YTHDF1 in cervical cancer, immunohistochemistry (IHC) assay was used to detect the expression of YTHDF1 protein in 10 pairs of cervical cancer and normal cervical epithelial tissues." (PMID 33816306, 2021). "In this study, YTHDF1 mediates the up-regulation of RANBP2 in an m6A-dependent manner in cervical cancer." (PMID 33816306, 2021). "Our study demonstrated the oncogenic role of YTHDF1 in cervical cancer by regulating RANBP2 expression and YTHDF1 represents a potential target for cervical cancer therapy." (PMID 33816306, 2021). "Collectively, these results suggested that YTHDF1-m6A-RANBP2 axis plays a significant role in cervical cancer." (PMID 33816306, 2021). "Taken together, these data demonstrated that the m6A reader YTHDF1 is highly expressed in cervical cancer and is related to the poor prognosis of cervical cancer patients." (PMID 33816306, 2021).
cervical carcinoma (continued). "Results showed that the expression of several m6A regulators was changed in cervical cancer, among which YTHDF1 expression was increased most significantly." (PMID 33816306, 2021). "Combined with on-line data analysis, RANBP2 is identified as the key target of YTHDF1 in cervical cancer cells." (PMID 33816306, 2021). "Colony formation assays displayed that YTHDF1 knockdown decreased the colony formation ability of cervical cancer cells." (PMID 33816306, 2021). "Through combined on-line data analysis of RIP-seq, meRIP-seq and Ribo-seq upon YTHDF1 knockdown, RANBP2 was identified as the key target of YTHDF1 in cervical cancer cells." (PMID 33816306, 2021). "By analyzing the two GEO datasets (GSE63514 and GSE52904) and the Biewenga Cervix dataset of the Oncomine database, we found that YTHDF1 was highly expressed in cervical cancer compared to normal cervical epithelial cells." (PMID 33816306, 2021). "Western blot analysis and RT-qPCR results showed that YTHDF1 was effectively knocked down in both cervical cancer cells." (PMID 33816306, 2021). "YTHDF1 knockdown suppressed the growth, migration and invasion, and induced apoptosis of cervical cancer cells." (PMID 33816306, 2021). "The correlation analysis suggested that there was a positive correlation between the protein expression of RANBP2 and YTHDF1 in cervical cancer." (PMID 33816306, 2021). "We investigated the DNA methylation at the YTHDF1 promoter and found that DNA methylation was negatively correlated with YTHDF1 expression in cervical cancer." (PMID 33816306, 2021). "Prior research has shown that suppressing YTHDF1 leads to apoptosis in cervical carcinoma." (PMID 39821576, 2025). "RIP-PCR assay indicated that YTHDF1 strikingly bound with the MCT1 mRNA in cervical cancer." (PMID 39557826, 2024). "In conclusion, these findings unveil the immune escape-promoting effect of YTHDF1 in cervical cancer by boosting the lactate accumulation, which might illuminate a novel target for more precise immunotherapy." (PMID 39557826, 2024). "METTL3 maintained HK2 stability via YTHDF1-mediated m6A, driving Warburg effect in cervical cancer." (PMID 39060874, 2024). "In the cervical cancer cells, the YTHDF1 mRNA significantly upregulated." (PMID 39557826, 2024). "Therefore, the immunosuppressive role of YTHDF1 in cervical cancer immune microenvironment is identified in this research and data." (PMID 39557826, 2024). "In conclusion, these findings unveil the immune escape-promoting effect of YTHDF1 in cervical cancer via lactate accumulation, which might illuminate a novel target for more precise immunotherapy." (PMID 39557826, 2024). "However, the function and significance of N6-methyladenosine (m6A) reader YTHDF1 in cervical cancer cells’ lactate metabolism and immunotherapy remain obscure." (PMID 39557826, 2024). "For example, FTO, METTL3, and YTHDF1 could promote the progression and metastasis of cervical cancer and are potential biomarkers for the prognosis of cervical cancer." (PMID 35432630, 2022). "Among these, YTHDF1 tends to stabilize the transcript and promote mRNA translation, while several studies have demonstrated that METTL3 enhances targeted mRNA stability and translation in a YTHDF1-dependent manner in cervical cancer, oral squamous cell carcinoma and liver cancer." (PMID 34996469, 2022). "We speculated that low expressed TRPV1 promotes cervical cancer tumorigenesis through YTHDF1/2/3, HNRNPA2B1, YTHDC1/2, ZC3H13, and METTL14 modification." (PMID 36072430, 2022). "In addition, transwell assays revealed that the migration and invasion of cervical cancer cells were significantly suppressed upon YTHDF1 depletion." (PMID 33816306, 2021). "Moreover, we performed Kaplan-Meier survival analysis and found that cervical cancer patients with high expression of YTHDF1 had the poor recurrence-free survival (RFS)." (PMID 33816306, 2021). "YTHDF1 is indispensable for the proliferation and metastasis of cervical cancer cells." (PMID 33816306, 2021).
cervical carcinoma (continued). "YTHDF1 aggravates cervical cancer progression through m6A-mediated RANBP2 upregulation." (PMID 34677810, 2021). "We also found that YTHDF1 knockdown induced apoptosis of cervical cancer cells." (PMID 33816306, 2021). "The subcutaneous tumor formation assays in nude mice also showed that YTHDF1 could promote the tumorigenesis of cervical cancer cells." (PMID 33816306, 2021). "Consequently, YTHDF1 emerges as a promising therapeutic target for cervical cancer treatment." (PMID 40271196, 2025). "Thus, it could be drawn a conclusion that YTHDF1 plays multi-dimensional oncogenic functions on cervical cancer." (PMID 39557826, 2024). "Moreover, the production of cytolytic granzyme B was tested and results indicated that CD8+ T cells incubated with YTHDF1 high-expression transfected cervical cancer cells secreted significantly lower amounts of granzyme-B than that YTHDF1 silencing transfection." (PMID 39557826, 2024). "YTHDF1 might represent a potential target for cervical cancer therapy." (PMID 33816306, 2021). "Moreover, YTHDF1 knockdown inhibited tumorigenesis of cervical cancer cells in vivo." (PMID 33816306, 2021). "Furthermore, the colony formation ability and proliferation of YTHDF1-overexpressing Hela and Siha cells were significantly increased, whereas knockdown of RANBP2 could compromise the effect of YTHDF1 overexpression on cervical cancer cells." (PMID 33816306, 2021). "Specifically, the up-regulation of RANBP2 expression induced by YTHDF1 potentially augments RAN-GTPase activity, thereby exacerbating the progression of cervical cancer." (PMID 40271196, 2025). "to upregulate HK2 protein expression through altering YTHDF1/HK2, increasing levels of glycolysis and encouraging the onset and progression of cervical cancer." (PMID 39661501, 2024). "YTHDF1 binds with the MCT1 via the m6A-modified site to enhance its mRNA stability, thereby promoting the lactate accumulation, thereby potentiating cervical cancer cells immune escape in MCT1-dependent manner." (PMID 39557826, 2024). "In cervical cancer, the expression level of HK2 (hexokinase 2) is also regulated by the collaborative action of YTHDF1 and METTL3." (PMID 38202722, 2023). "In the context of cervical cancer, the translation of the PDK4 protein is also under the regulatory influence of YTHDF1." (PMID 38202722, 2023). "Previous studies have shown that YTHDF1 expression can promote the glycolytic ability of LUAD and cervical cancer cells, so as to enhance the proliferation of tumor cells." (PMID 35401696, 2022). "Another study discovered that the YTHDF1/eEF-2 complex and IGF2BP3 increase the translation elongation and mRNA stability of pyruvate dehydrogenase kinase 4 to control glycolysis in cervical cancer cells." (PMID 36091006, 2022). "The prognostic signature-based riskscore (METTL16, YTHDF1, and ZC3H13) was found to be an independent prognostic indicator of cervical cancer." (PMID 36091006, 2022). "In human cervical cancer tissues, the expression of PD-L1, METTL16, ZC3H13, and YTHDF1 was highly expressed in cervical cancer patients compared with surrounding normal tissues." (PMID 36091006, 2022). "Three m6A regulators (METTL16, YTHDF1, and ZC3H13) were chosen as the minimum standard for constructing a predictive signature, and the riskscore of each cervical cancer patient was determined." (PMID 36091006, 2022). "YTHDC1 and YTHDF1 have anti-cancer effects in cervical cancer, while ZC3H13, WTAP, HNRNPC, YTHDF3 and VIRMA have tumor-promoting effects in cervical cancer." (PMID 35581263, 2022). "In conclusion, our study showed that the m6A “reader” YTHDF1 promotes the proliferation, migration and invasion of cervical cancer cells, and we also identified RANBP2 as the direct target of YTHDF1." (PMID 33816306, 2021). "YTHDF1 regulated RANBP2 translation in an m6A-dependent manner, which plays an important role in cervical cancer." (PMID 33816306, 2021).
cervical carcinoma (continued). "Therefore, YTHDF1 might be a potential target for cervical cancer treatment." (PMID 33816306, 2021). "Thus the high expression of YTHDF1 in cervical cancer may be partially due to DNA hypomethylation." (PMID 33816306, 2021). "Consistently, IGF2BP3 and YTHDF1, the readers of PDK4 mRNA, significantly increased in cervical cancer tissues as compared with that in the normal control samples." (PMID 32444598, 2020). "Moreover, m6A modification mediated by YTH domain-containing family protein 1 (YTHDF1) increased the stability of HK2 and promoted the Warburg effect of cervical cancer cells." (PMID 39991762, 2025). "The co-location of YTHDF1 and MCT1 was investigated using RNA fluorescence in situ hybridization (FISH) and data indicated that YTHDF1 and MCT1 consistently distributed in the cytoplasm of cervical cancer cells." (PMID 39557826, 2024). "Moreover, the oncogenic role of YTHDF1 was observed to influence the upregulation of RANBP2 mRNA and enhance the progression of cervical cancer in an m6A-dependent manner." (PMID 37259333, 2023). "Moreover, METTL3 recruited YTHDF1 to enhance HK2 stability, thereby promoting the Warburg effect of cervical cancer." (PMID 34185971, 2022). "This study indicated that METTL16, YTHDF1, and ZC3H13 could regulate the expression of PD-L1 in cervical cancer." (PMID 36091006, 2022). "Furthermore, this study created a three-gene prognostic marker consisting of an m6A methylation regulatory factor, namely, METTL16, YTHDF1, and ZC3H13, and the calculated riskscore had a good predictive effect on cervical cancer patients." (PMID 36091006, 2022). "Moreover, downregulation of METTL16, YTHDF1, or ZC3H13 in two cervical cancer cell lines elevated the expression of PD-L1." (PMID 36091006, 2022). "RANBP2 expression up-regulated by YTHDF1 might enhance the activity of RAN GTPase activity and aggravate the progress of cervical cancer, which might need more investigations in further study." (PMID 33816306, 2021). "The m6A methyltransferase METTL3 links to the 3’-untranslated region of HK2 mRNA and recruits YTHDF1 to ensure HK2 stability, ultimately boosting aerobic glycolysis in cervical cancer (CC) cells, contributing to their proliferation and leading to poor prognosis in cervical cancer." (PMID 37055798, 2023). "YTHDF1 regulates the translation of RANBP2 in an m6A-dependent manner, but not its mRNA expression, thereby affecting cervical cancer cell growth, migration, and invasion." (PMID 39342406, 2024). "YTHDF1 regulated the translation of RANBP2, which potentiated the growth, migration, and invasion of cervical cancer cells in an m6A-dependent manner without any effect on its mRNA expression." (PMID 36058934, 2022).